INS (insulin)
Diseases named in the same sentence as INS in open-access papers (continued):
Sharing a sentence is not in itself a finding about the gene and the disease.
Obesity (continued). "Also, increased insulin could cause obesity rather than a product." (PMID 35757631, 2022). "Night sleep duration is correlating with insulin level but total 24-h day sleep did not correlate with any glycemia parameters or obesity." (PMID 36299550, 2022). "A recent clinical study with the SGLT2i empagliflozin reported improved hypothalamic insulin sensitivity in subjects with prediabetes and obesity, although the study was not randomized in a sex‐stratified manner." (PMID 35707855, 2022). "Indeed, the PI3K-AKT signaling pathway, a well-known regulator of cancer metabolism, is regulated by several growth factors, such as insulin, IGF-1, and leptin, whose levels are modified in obesity." (PMID 35158830, 2022). "It demonstrated that the transplantation of intestinal microflora from lean human donors could improve insulin sensitivity in recipients, and further cemented the potential role of FMT in obesity treatment." (PMID 36439220, 2022). "Overall, our findings implicate G6PC2 as a potential therapeutic target for enhancing insulin secretion and lowering FBG, which could benefit individuals with prediabetes, T2D, and obesity." (PMID 35176280, 2022). "Overall, central insulin action increased the BOLD response in the amygdala, while several other food-cue responsive regions, as the insular cortex, showed interactions between sex and obesity on how insulin affected FCR." (PMID 35715625, 2022). "Indeed, administration of A. muciniphila (daily 5 × 109 cfu/mL) in animal models of obesity, such as HFD mice, reduced insulin sensitivity, fat deposition, and weight gain." (PMID 35208906, 2022). "For instance, MKP-1 whole-body knockout mice were resistant to diet-induced obesity but not insulin sensitive, and MKP-3 regulates hepatic gluconeogenesis and increased MKP-4 expression in adipose tissue of db/db mice." (PMID 35745205, 2022). "Remarkably, overproduced interleukin-6 (IL-6) from adipose tissue macrophages (ATM) in obesity accounts for elevated basal lipolysis, which leads to production of excessive acetyl-CoA in the liver eliciting hepatic glucose production (HGP) and insulin insensitivity in mice." (PMID 36276810, 2022). "Also, L-carnitine significantly affected insulin (pmol/l), HOMA-IR (%), and HbA1c (%) in trial duration ≥12 weeks, intervention dose ≥2 g/day, and participants with obesity (baseline BMI >30 kg/m2)." (PMID 36704801, 2022). "It is not so simple because DGKε-KO mice show severe obesity and insulin resistant phenotype under short-term (40 days) HFD feeding conditions." (PMID 35153836, 2022). "In addition, it is known that insulin can upregulate apelin expression in both human and murine adipocytes, suggesting the existence of a regulating loop where hyperinsulinaemia may promote apelin secretion during obesity as a compensatory mechanism to adapt to the enhanced insulin request." (PMID 35628332, 2022). "The participants were patients aged 40 to 70 years who were treated for T2DM (hemoglobin A1c [HbA1c] above 6.0%) without insulin or hypertension and obesity, controlled with pharmacotherapy." (PMID 35014961, 2022). "Leptin failed to improve insulin sensitivity in T2DM patients with obesity due to hyperleptinemia and leptin resistance." (PMID 34996484, 2022). "Its relationship to the Glucostatic Theory became more clear when it was found not to produce obesity in diabetic mice and was restored with insulin." (PMID 35662925, 2022). "Their findings showed that changes in fasting insulin preceded changes in weight gain and did not support the assertion that obesity comes first before elevated fasting insulin levels and disease development." (PMID 35458121, 2022). "Although adipose tissue is a central metabolic organ involved in the pathogenesis of obesity-related metabolic diseases, the potential health benefits of HTGT and EMIQ treatment, such as insulin sensitivity and anti-inflammatory effects in other metabolic organs, need further investigation." (PMID 35241108, 2022).
Obesity (continued). "With regard to the essential role of hepatic acetyl-CoA in the mediation of WAT-derived FFA in hepatic insulin insensitivity, we hypothesized that Phillyrin treatment could reduce the FFA flux from dysfunctional WAT to liver in obesity." (PMID 36276810, 2022). "Furthermore, women with overweight and obesity and men of normal weight showed higher BOLD neural food cue responsivity to central insulin compared to placebo." (PMID 35715625, 2022). "In contrast, pancreatic β cell-specific Pcsk1 ablation leads to profound hyperphagic obesity mediated by the lack of mature insulin." (PMID 35963866, 2022). "An earlier study suggested that it was not obesity itself, but rather its metabolic complication, that is, insulin resistance that was responsible for CVRCO2 impairment." (PMID 36158536, 2022). "By releasing pro-inflammatory signaling factors, the white adipose tissue greatly contributes to the obesity-mediated homeostatic disruption, leading to multiple negative functional consequences (e.g., insulin resistance)." (PMID 35453491, 2022). "Obesity develops not due to impaired pro-islet amyloid polypeptide processing but due to impaired insulin maturation." (PMID 35963866, 2022). "As a consequence of lower obesity and mild peripheral IR observed in the Charles River fa/fa rats compared to the Envigo fa/fa rats manifested by decreased QUICKI, there was only a mild impairment of hippocampal insulin signaling." (PMID 35589696, 2022). "Indeed, many of the protein superfamilies modulated by resveratrol are relevant for obesity and metabolic diseases, including SIRT1 and proteins related to nitric oxide (NO), insulin, and nuclear hormone receptors (such as PPARγ)." (PMID 35889827, 2022). "In this context, GLP-1 may potentially be influenced by changes in aquaporin-7 expression, which has been noted to be downregulated after VSG in rats with obesity and may result in GLP-1-induced pancreatic steatosis improvement and insulin secretion." (PMID 35328759, 2022). "In line with such an assumption, we confirmed data revealing a relationship of Fetuin-B to estimates of obesity, liver fat, whole body, and myocellular insulin resistance, even if this was not described in all cohorts." (PMID 34611132, 2021). "We hypothesize that hepatic GABA production in obesity decreases HVAN activity to limit muscle glucose clearance and drive peripheral insulin resistance." (PMID 34192533, 2021). "In hyperinsulinemic states, such as obesity, not all tissues and not all pathways are insulin resistant." (PMID 33400689, 2021). "In the univariate analysis, previous macrosomia history, pre-pregnancy obesity, excessive gestational weight gain, higher fasting blood glucose in the 1st trimester and at 0' in the OGTT, need for insulin therapy, and higher third trimester HbA1c were factors associated with LGA." (PMID 33939909, 2021). "In conclusion, firstly, 4 weeks of exercise training did not alter gastric emptying, glucose, insulin, ghrelin or subjective appetite ratings in the present study of inactive men with overweight and obesity." (PMID 34124120, 2021). "Importantly, in the subgroup analysis for the participants who already had overweight or obesity at baseline, the results showed the CR–RS combined intervention was superior to either CR or RS in improving SBP, DBP, IL-8, insulin, and HOMA-IR levels." (PMID 34579097, 2021). "In insulin-resistant humans and mouse models of diet-induced or genetic obesity, changes in ATG gene expression and protein content have been observed in insulin target tissues, although a causal role has not been established." (PMID 34336862, 2021). "Another study of children and adolescents with obesity reported a negative correlation of sclerostin level with both fasting insulin and HOMA-–IR." (PMID 34572220, 2021). "Periodized and non-periodized combined exercise training similarly reduces insulin resistance markers in adults with obesity." (PMID 34568974, 2021).
Obesity (continued). "ob/ob mice lacking PI3Kγ, and mice with diet-induced obesity lacking PI3Kγ in leucocytes and endothelial cells did not display improved insulin sensitivity, steatosis, metabolic inflammation, or reduced tumour growth." (PMID 34704005, 2021). "In addition, the blood biochemical profiles including fasting glucose, fasting insulin and HOMA-IR were unfavorably altered, thus confirming the state of IR and obesity." (PMID 34889901, 2021). "On the other hand, the use of sulphonylureas and insulin for the treatment of T2DM can result in weight gain, which is a big challenge in individuals with obesity and may result in delaying treatment intensification, leading to clinical inertia." (PMID 34401196, 2021). "The goal of managing susceptible horses is to prevent exposure to suspected laminitis risk factors and triggers; obesity, pasture rich in non-structural carbohydrates (NSC), and insulin dysregulation, and to preserve the optimal hoof conformation." (PMID 34048478, 2021). "Prohibitin (PHB) has been shown to play a role in the disruption of obesity related insulin homeostasis in males, but not in females." (PMID 34771149, 2021). "The extent to which these molecular mechanisms of GSH and ROS contribute to obesity in humans and may be regulated through dietary means needs further research, though it has been demonstrated that elevated GSH reduces insulin sensitivity in adipocytes." (PMID 34960018, 2021). "We hypothesize that diet-induced obesity would increase the PTP1B content in the liver of obese animals and impair hepatic insulin sensitivity due to the reduction of IRS-1/2 phosphorylation." (PMID 34203825, 2021). "On the contrary, no influence of leptin levels on the differences in NEFA and insulin concentrations between children with and without obesity was observed in 12- to 16-year-old children." (PMID 35071145, 2021). "One particularly intriguing difference that has received attention is the observation that transcriptional responses to acute exercise are related to insulin sensitivity but are independent of obesity." (PMID 33897458, 2021). "Although a significant interaction effect was observed for insulin sensitivity, this was likely due to a reduction in insulin sensitivity for individuals without obesity, and not from an improvement in individuals living with obesity." (PMID 34110721, 2021). "Metabolic and microvascular insulin responses are important mutual predictors in humans, at least in populations that include people who are lean, have class 1 obesity or controlled T1D but without other major comorbidities." (PMID 34075130, 2021). "However, this reduced enteroid formation was reversed by insulin and IGF1, proposing that insulin/IGF-1 signaling mediates stemness acquisition of ISC in HFD-induced obesity." (PMID 33827616, 2021). "Due to these actions D-Chiro-Ins has been proposed to correct defective insulin function in a variety of conditions characterized by metabolic dysfunction, such as polycystic ovary syndrome (PCOS), obesity, gestational diabetes and fat accumulation at menopause." (PMID 33859622, 2021). "Recently, MSI-1436 has been shown to inhibit PTP1B—a key enzyme regulating insulin and leptin signaling, via a non-competitive allosteric mechanism, which improves insulin sensitivity and reduces obesity." (PMID 33536069, 2021). "In fact, increased acetate production by an altered gut microbiota leads to activation of the parasympathetic nervous system which in turn promotes increased glucose-stimulated insulin secretion (GSIS), increased ghrelin secretion, hyperphagia, obesity, and its related sequelae." (PMID 34458288, 2021). "Both insulin and glucose enhance the ATX release from adipocytes, suggesting that LPA aberrant signaling may be strictly related to obesity-dependent alterations." (PMID 33572982, 2021). "After adjusting by leptin, insulin levels remained significantly higher in adolescents with obesity as compared with levels in those without obesity." (PMID 35071145, 2021).
Obesity (continued). "Participants with overweight/obesity were older, had higher total daily insulin dose, and higher prevalence of hypertension compared to normal BMI." (PMID 34530819, 2021). "Furthermore, in murine models of obesity induced by high fat diet, TCPOBOP showed beneficial effects by improving insulin sensitivity and hepatic steatosis." (PMID 34502180, 2021). "Likewise, in a diet-induced obesity mouse model, the administration of IFN–tau, a member of IFN-I family, results in increased insulin sensitivity, decreased expression of pro-inflammatory cytokines and expansion of anti-inflammatory M2 macrophages." (PMID 33430520, 2021). "Preliminary evidence from in vivo studies and from epidemiologic reports suggest that obesity may affect BRCA penetrance through several mechanisms, including insulin resistance and insulin-like growth factor I (IGF-I) regulation." (PMID 34869002, 2021). "In patients with T2DM and obesity, insulin fails to appropriately regulate hepatic metabolism, leading to excess production of glucose despite accelerated rates of lipid synthesis, a condition commonly referred to as selective hepatic IR." (PMID 33918509, 2021). "With this mouse model, we found that the expression of huCETP improved hepatic and whole-body insulin sensitivity in female but not male mice during obesity." (PMID 35082691, 2021). "In fact, epidemiological studies suggest that approximately 50% of salt sensitive individuals are insulin resistant, independent of confounding factors such as age, obesity, and glucose intolerance." (PMID 34966295, 2021). "Insulin resistant conditions, including obesity and T2DM, may lead to chronic low-grade inflammation that can be inverted by pioglitazone therapy together with enhanced insulin action." (PMID 34037093, 2021). "Interestingly, germ free mice appear to be resistant to diet-induced obesity (High Fat Diet) and to have low levels of inflammatory cytokines (TNF alfa) and improved insulin sensitivity." (PMID 33668627, 2021). "Evidence has shown that NNMT plays important roles in obesity and T2D and that NNMT inhibition significantly increases energy expenditure, reduces body weight and white adipose mass, improves insulin sensitivity, and normalizes glucose tolerance and fasting blood glucose levels." (PMID 34368359, 2021). "Children with NI showed higher values of insulin, IR, TGs, and HDL-cholesterol (p < 0.001) compared to children of a normal weight, and significantly higher HOMA-IR compared to pediatric patients with obesity (p < 0.04)." (PMID 34287378, 2021). "The primary objective was to investigate changes in substrate oxidation at rest and during submaximal exercise, and in insulin sensitivity after 4 weeks of SIT in individuals living with or without obesity." (PMID 34110721, 2021). "Taken together, our findings suggest that inulin supplementation had no obvious impact on peripheral insulin sensitivity, but the impact on HOMA-IR in adults with overweight and obesity at increased risk of T2D in the present study is unclear." (PMID 34579112, 2021). "AM‐induced microbiome alterations have been linked to dysregulation of metabolism, for example inducing low‐grade inflammation, decreasing insulin sensitivity and altering short‐chain fatty acid (SCFA) and bile acid metabolism, which are also present in obesity." (PMID 32959492, 2021). "Contrary to WAT grafts, which mainly improve glucose tolerance or insulin sensitivity, BAT grafts may also aid in decreasing excessive fat storage and targeting obesity directly by increasing the organism’s energy expenditure and heat production." (PMID 35052704, 2021). "Although the effect was relatively small for some indicators of obesity, notably, the effect of replacing SED with PA using the ISM method on metabolic health was positive for indicators of obesity, BP, blood lipids, glucose, and insulin." (PMID 34200736, 2021).
Obesity (continued). "In conclusion, maternal C-peptide and insulin sensitivity (ISHOMA), but not proxies of obesity such as BMI or leptin, associate with serum n-3 PUFA." (PMID 34638763, 2021). "Thus, defects in insulin signaling network in obesity are difficult to modify, as suggested by our findings of changes only in the IR after either WL or AEX on the MAPK and insulin signaling pathways." (PMID 34943997, 2021). "In the current study, the aim was to determine the effect of 16 weeks of combined training with and without linear periodization on insulin resistance indicators in adults with obesity." (PMID 34568974, 2021). "Our data showed that lack of AKAP1 signaling significantly alleviated HFD‐induced adiposity, decreased ectopic fat accumulation in liver, improved blood metabolic parameters and insulin sensitivity, indicating AKAP1 as a driving force for diet‐induced obesity and metabolic dysfunctions." (PMID 33747723, 2021). "This indicates a dissociation—which can be mechanistic or just temporal—between abnormalities in insulin action and in lipid and lipoprotein metabolism in the absence of obesity." (PMID 33718425, 2021). "According to age (years) categories, we found that blood pressure, fasting blood glucose, lipids, obesity markers (BMI, body fat, WC, HC and WHR), fasting insulin and HOMA-IR was significantly higher in 45–60 years group as compared to 20–45 years group (p<0.05)." (PMID 34449768, 2021). "Experimental evidence suggest that FFAR-targeted therapies offer the potential to reduce hyperglycemia without inducing hypoglycemia, promote insulin sensitivity, reduce obesity, and prevent hepatic lipotoxicity." (PMID 33897464, 2021). "Two studies in full cohorts of women with overweight/obesity have observed no change in insulin sensitivity, assessed by OGTTs or the hyperinsulinemic-euglycemic clamp, when measured 72 h following 6–14 weeks of low-volume HIIT." (PMID 34940959, 2021). "Non-esterified fatty acids (NEFA), insulin resistance, lactic acid after training in subjects with obesity." (PMID 34047810, 2021). "In the case of obesity and hyperinsulinemia, a decrease in PI3K activation may be a key step in supporting the increase in insulin-induced vasoconstriction." (PMID 34470604, 2021). "Eight weeks of treatment of diazoxide to hyperinsulinemic obese humans induced greater attenuation of acute insulin responses to glucose and significant anti-obesity effects without inducing significant differences in insulin sensitivity and glucose levels." (PMID 34360563, 2021). "The Ren1c−/− mice are lean, insulin sensitive, and are resistant to diet-induced obesity without changes in food intake and physical activity." (PMID 34107965, 2021). "Even though no significant improvement in insulin sensitivity was observed for those living with obesity, these data shed light on potential improvements in glucose metabolism in this BMI group." (PMID 34110721, 2021). "Other signals such as EGF, BDNF, FGF, other growth factor signals, autonomic neuronal signals, myokines, muscle damage, pain and infection have been shown to affect insulin sensitivity partly or completely independent of obesity." (PMID 33544739, 2021). "In this context, it was reported by several authors a negative relationship between obesity and IL-10 levels; in some cases, this cytokine correlated positively with energy homeostasis and negatively with insulin resistance." (PMID 34568404, 2021). "In a comparison of age-, sex-, and BMI-matched patients with metabolically healthy obesity either with preserved insulin sensitivity or insulin resistance, we found that neither CCL2 serum concentrations nor AT expression are related to AT inflammation." (PMID 33540898, 2021). "In previous studies, we described that males and females with obesity had higher plasma insulin levels and HOMA values than their non-obese counterparts in prepubertal as well as in 12- to 16-year-old children." (PMID 35071145, 2021).